NFKBID (NFKB inhibitor delta)
Description:
Regulates the expression of IL-2, IL-6, and other cytokines through regulation on NF-kappa-B activity. Functions in the regulation of inflammatory responses. Involved in the induction of T helper 17 cells (Th17) differentiation upon recognition of antigen by T cell antigen receptor (TCR). May also regulate TCR-induced negative selection of thymocytes.
Synonyms: IKBNS; TA-NFKBH; IkappaBNS
Tractability: Antibody: the Human Protein Atlas places it where antibodies can reach. PROTAC: its protein half-life has been measured.
Gene: Protein-coding gene on chromosome 19 (35,887,630 to 35,902,303, reverse strand). Ensembl gene ENSG00000167604.
Subcellular location: Nucleus
Subcellular location (Human Protein Atlas): Cytosol; Nuclear bodies; Plasma membrane
Gene Ontology:
Molecular function: protein binding
Biological process: positive regulation of T-helper 17 cell differentiation; regulation of gene expression; T cell receptor signaling pathway
Cellular component: nucleus
Genetic constraint (gnomAD): Loss-of-function variants: 24 observed, 47.93 expected, observed/expected ratio (o/e) 0.5, 90% interval 0.36 to 0.7. The upper end of that interval is the gene's LOEUF score, 0.7, which puts it in group 2 of 6, group 1 being the genes least tolerant of losing a copy. Missense variants: 452 observed, 569.71 expected, observed/expected ratio (o/e) 0.79, 90% interval 0.73 to 0.86. Synonymous variants: 238 observed, 240.69 expected, observed/expected ratio (o/e) 0.99, 90% interval 0.89 to 1.1.
Homologues: Orthologues: chimpanzee NFKBID (96% identical), macaque NFKBID (94% identical), dog NFKBID (87% identical), pig NFKBID (87% identical), mouse Nfkbid (82% identical), rat Nfkbid (80% identical), guinea pig NFKBID (61% identical), rabbit NFKBID (61% identical), tropical clawed frog nfkbid (40% identical). Paralogues in human: NFKBIZ (34% identical), ANKRA2 (15% identical), RFXANK (13% identical).
Diseases named in the same sentence as NFKBID in open-access papers:
NFKBID is named in the same sentence as 15 diseases in open-access papers, as found by Europe PMC text mining. Sharing a sentence is not in itself a finding about the gene and the disease. The quoted sentences say what the papers report.
COVID-19 (2 papers, 2020 to 2021). A disease caused by infection with severe acute respiratory syndrome coronavirus 2. "The downregulated genes include ones mediating immune signaling, e.g., RIPK2, RLRP3, and NFKBID, etc., and genes encoding cytokine and chemokines, suggesting impaired immune functions of monocytes from COVID-19 patients." (PMID 35095917, 2021).
colorectal cancer (1 paper, 2025). A primary or metastatic malignant neoplasm that affects the colon or rectum. "This study addresses a critical gap in understanding colorectal cancer (CRC) radiation resistance by identifying BAMBI, GADD34, NFKBIA, and NFKBID as key modulators of tumor progression and response to radiotherapy." (PMID 40332515, 2025).
E. coli infection (1 paper, 2017). "Such factors having exclusively been induced by the E. coli infection included several TNFα induced proteins (TNFAIP230; TNFAIP331, also known as ubiquitin-editing enzyme A20; TNFAIP632) the suppressors of cytokine signaling SOCS1, SOCS333 and the NF-κB inhibitors NFKBIA, NFKBID, NFKBIE34." (PMID 28684793, 2017).
lymphoma (1 paper, 2020). A malignant (clonal) proliferation of B- lymphocytes or T- lymphocytes which involves the lymph nodes, bone marrow and/or extranodal sites. "We also detected changes in the expression of proteins involved in the proliferation-related mTOR and NF-κB pathways, such as LAMTOR1 and NFKBID, which was consistent with a previous study describing a multiprotein supercomplex involved in the control of oncogenic signaling in lymphoma." (PMID 32546241, 2020).
infection (5 papers, 2019 to 2025). The state of being infected such as from the introduction of a foreign agent such as serum, vaccine, antigenic substance or organism. "Our RNA-seq analysis shows that several inhibitors of the NF-kB and MAPK signaling pathways were significantly down-regulated 36 days after infection, including NFKBID, NFKBIZ, DUSP-1, -2, NR4A2, and tristetraprolin (TTP or ZFP36)." (PMID 33324683, 2020). "We ranked the top 10 most upregulated and downregulated genes in each cellular subpopulation and noted the upregulation of inflammation-related genes, such as NFKBIA and NFKBID, suggesting that infection with H. contortus may induce an inflammatory response in the host." (PMID 38786064, 2024). "On the other hand, NFKBID is a component of the Th17/Treg NF-κB signaling cascade and is essential for Th17 differentiation in response to inflammation and infection, although it does not appear to influence apoptosis." (PMID 40332515, 2025).
NFKBID also shares sentences with these, for which no sentence is quoted: Autoimmunity (2 papers); Listeria monocytogenes infection (2); tumor (2); ankylosing spondylitis (1); atherosclerosis (1); autoimmune disease (1); immunodeficiencies (1); infectious disease (1); type 1 diabetes (1); viral infections (1).